INS (insulin)
Diseases named in the same sentence as INS in open-access papers (continued):
Sharing a sentence is not in itself a finding about the gene and the disease.
diabetes (continued). "Diabetes mellitus (DM) is a metabolic disease defined as chronic hyperglycemia caused by insulin resistance (IR) or compromised insulin production." (PMID 35052818, 2022). "Diabetes is actually a general term, representing multiple organ involvement and carbohydrate metabolism disorders that is manifested with elevated blood sugar and elevated levels of urine glucose due to insulin secretion deficiency or insulin dysfunction, or both." (PMID 36311276, 2022). "Diabetes mellitus (DM) is a metabolic disorder characterized by hyperglycemia that is caused by insulin resistance or declined insulin secretion." (PMID 35746917, 2022). "Thus, the overexpression of Srebf1 and Srebf2 has been shown to cause beta cell dysfunction and eventually diabetes, which at the cellular level is reflected by the repression of Pdx1 expression, impaired insulin secretion and content, as well as cellular triglyceride and cholesterol accumulation." (PMID 36232358, 2022). "During the early stages of diabetes, islet β cells are exposed to the inflammatory environment formed by pro-inflammatory cytokines; under these conditions, miR-29 overexpression inhibits the expression of the transcription factor, Onecut2, which is associated with defective insulin secretion." (PMID 36561684, 2022). "Diabetes mellitus (DM) is a chronic metabolic disorder and an inappropriate hyperglycemia due to either insulin secretion deficiency or a combination of insulin resistance and inadequate insulin secretion to compensate blood glucose levels." (PMID 35011523, 2022). "Type 2 diabetes mellitus (DM) may be defined as a cluster of metabolic ailments arising from abnormalities in the metabolism of carbohydrates and/or lipids which result in a deficient insulin secretion and subsequent insulin resistance." (PMID 36555696, 2022). "Conventionally, the relationship between diabetes and pancreatic cancer was thought to be caused by pancreatic tissue destruction caused by concomitant pancreatitis caused directly by pancreatic cancer or by obstruction of the pancreatic duct, resulting in decreased insulin secretion." (PMID 36140658, 2022). "The question arises whether changes in liver insulin degradation are normal—and therefore protective of the organism—or whether they may be abnormal, possibly leading to conditions of metabolic risk, such as impaired glucose tolerance and/or diabetes itself." (PMID 35163746, 2022). "Diabetes mellitus (DM) is a metabolic disease, which arises from a complete deficiency of insulin production—type 1 diabetes (T1D)—or inability to utilize this hormone, as occurs in type 2 diabetes (T2D)." (PMID 35840987, 2022). "In streptozotocin diabetes-induced rat models, T. violacea attenuated diabetes-associated physiological conditions resulting in improved body weights, reduced fasting blood glucose levels, enhanced glucose tolerance and significantly elevated plasma insulin and liver glycogen content." (PMID 35889346, 2022). "Diabetes mellitus (DM) is a metabolic disease that causes high blood glucose due to the body’s inability to produce sufficient or functional hormone insulin to regulate blood glucose." (PMID 36144493, 2022). "Catechins may be effective in controlling hyperglycaemia and preventing complications in diabetes by improving insulin susceptibility and reducing certain type 2 diabetes risk factors such as oxidative stress, dyslipidaemia, and obesity—as evidenced in both human and animal studies." (PMID 35743146, 2022). "Besides, other relevant studies pointed that the use of insulin could worsen outcomes of CRC patients with preexisting diabetes, in which the use of insulin was associated with more lymphatic metastasis and more advanced pathological stage." (PMID 35296101, 2022).
diabetes (continued). "Carrageenan might also be associated with the development of diabetes; it was shown in an in vivo and in vitro investigation that exposure to carrageenan led to an impairment in glucose intolerance and a rise in both insulin resistance and insulin signaling." (PMID 35745095, 2022). "Diabetes mellitus (DM) is a chronic metabolic disorder of carbohydrates, lipids, and proteins due to a deficiency of insulin secretion or failure to respond to insulin secreted from pancreatic cells, which leads to high blood glucose levels." (PMID 36556443, 2022). "Type 2 diabetes mellitus (T2DM), caused by impaired insulin secretion and insulin resistance, accounts for more than 90% of all the incidences and is the most prevalent form of DM." (PMID 35337127, 2022). "Additionally, insulin sensitizer medication use (metformin and/or thiazolidinediones) may attenuate muscle loss in men with impaired fasting glucose and diabetes." (PMID 34983489, 2022). "In diabetes mellitus, a reduction in body weight and a rise in food and water consumption are usually observed due to the destruction of β-cells, which may be due to metabolic changes triggered by a lack or deficiency of insulin." (PMID 36558918, 2022). "Diabetes mellitus (DM) is a metabolic disease characterized by hyperglycemia and is caused by insulin resistance or inadequate insulin secretion." (PMID 35869471, 2022). "Moreover, insulin signaling pathway-associated proteins can induce both osteoporosis and diabetes." (PMID 35328013, 2022). "Diabetes mellitus (DM) is a clinical syndrome characterized by hyperglycemia due to absolute or relative deficiency of insulin." (PMID 35655687, 2022). "Elevated blood glucose levels (BGL) brought on by deficiencies in insulin secretion, action, or both characterize the metabolic disease known as diabetes mellitus (DM)." (PMID 36337582, 2022). "Overall, our study suggests that in insulin-deficient diabetes, diet-induced ketosis might attenuate the responsiveness of the hypothalamic OX neurons to recurrent hypoglycemia by mechanisms that most likely do not involve and/or do not affect the sympathoadrenal catecholamine response." (PMID 36676967, 2022). "The relationship between IR and/or T2D, obesity, and thyroid cancer has been recently explored and, although the etiology of such an association is unclear, it may involve high insulin levels, increased body fat, hyperglycemia, and anti-diabetes medications including exogenous insulin use." (PMID 35740085, 2022). "Insulin resistance (IR) is characterized by an impaired glucose metabolic response to a given amount of insulin and is considered to contribute to the development of diabetes mellitus (DM) and to be a major risk factor for cardiovascular diseases." (PMID 35651853, 2022). "The anabolic effect of insulin on muscle mass in combination with adequate amino acids intake could be an effective countermeasure for muscle loss, not only for people who suffer from diabetic mellitus, but generally for older adults." (PMID 35736019, 2022). "Diabetes mellitus (DM) is a chronic metabolic disease characterized by reduced insulin sensitivity or insulin deficiency, causing blood hyperglycemia in the postprandial and fasting state." (PMID 36105200, 2022). "When taken into the context of our current data, it is plausible to conclude that the beneficial renal actions of ROCK2 inhibition in diabetes may be due to the re-sensitization of podocytes to insulin signaling or prevention of metabolic stress in association with the recovery of FAO." (PMID 35396346, 2022). "Diabetes Mellitus (DM) is a worldwide health problem characterized by high blood glucose levels caused by a defect in insulin production or insulin resistance, or both." (PMID 36120460, 2022).
diabetes (continued). "While, silencing of circHIPK3 and ciRS-7/CDR1 in the small patches of normal mice caused impaired insulin secretion, poor rate of β-cell proliferation, and lower survival rate, indicating a possible role of transformed expression of circHIPK3 and ciRS-7 in the development of diabetes mellitus." (PMID 35184688, 2022). "For instance, while it is generally believed that the etiology of diabetes in Southeast Asian diabetic patients points to especially poor insulin resistance, recent reports have indicated that a large sub-group of patients belong to an insulin-deficient phenotype." (PMID 35624890, 2022). "Glutamine was previously thought to be associated with obesity and diabetes, as higher levels of glutamine and related metabolites are part of the systematic response to higher blood glucose levels and act to stimulate insulin secretion to lower blood glucose levels." (PMID 36560955, 2022). "Insulin plays a fundamental role in metabolic homeostasis and its dysregulation underlies many metabolic disorders, including diabetes mellitus (DM) and cardiometabolic complications." (PMID 35177603, 2022). "The characteristic of diabetes mellitus (DM) is hyperglycemia brought on by a deficiency in insulin, an inability to utilize insulin, or both." (PMID 36505102, 2022). "Recent evidence also showed that they are associated with an increased incidence of diabetes, which might be related to their effect of decreasing insulin sensitivity by lowering plasma adiponectin levels in a dose-dependent manner, thereby leading to an approximately 20–30% higher risk of diabetes." (PMID 35722157, 2022). "Recent studies have linked insulin resistance (IR) and impaired insulin signaling to the cross-talk between diabetes mellitus (DM) and Alzheimer’s disease (AD)." (PMID 36316461, 2022). "Therefore, a decrease in insulin secretion or sensitivity can cause diabetes." (PMID 35207724, 2022). "Diabetes mellitus (DM) is a chronic systemic metabolic disease characterized by hyperglycemia and is caused by defective insulin secretion and/or insulin resistance (IR)." (PMID 36439213, 2022). "Diabetes mellitus (DM) is a metabolic disease characterized by high blood sugar caused by insufficient insulin secretion (type I DM), insufficient insulin action (type II DM), or both." (PMID 35200309, 2022). "Furthermore, recent studies have reported that an abnormal quality of sleep is associated with a higher risk of metabolic syndrome and type II diabetes mellitus and that patients with uncontrolled diabetes and insulin users had a higher risk of poor quality of sleep." (PMID 35458120, 2022). "Diabetes mellitus (DM) is a metabolic disorder characterized chiefly by chronic hyperglycemia as a result of insulin secretion deficiency or insulin resistance." (PMID 36484062, 2022). "Diabetes mellitus (DM) is a metabolic disease with characteristic high plasma glucose concentration due to either insulin deficiency and/or impaired insulin activity." (PMID 35739183, 2022). "Interestingly, DLGAP2 and FAM13A, have previously been identified to have a role associated with diabetes and maternal insulin sensitivity in pregnancy, thus suggesting a possible function of their methylation in the future risk of obesity and T2D in offspring." (PMID 36452324, 2022). "Diabetes mellitus (DM) is a clinical syndrome characterized by chronic hyperglycemia due to inadequate insulin secretion and/or deficient insulin action." (PMID 35574009, 2022). "Diabetes mellitus (DM), a chronic disease due to insulin and its action deficiency or both, leads to delayed hyperglycemia, ultimately affecting metabolic processes inside the human body." (PMID 35204283, 2022). "This disease is caused due to diabetes mellitus (DM), which is defined by poor glucose metabolism due to insulin failure or resistance." (PMID 36298186, 2022).
diabetes (continued). "The most frequent types of DM are type 1 and type 2, with type 1 caused by the inability of the body to produce adequate insulin, whereas type II diabetes mellitus is characterized by fasting hyperglycemia due to insulin resistance." (PMID 35774744, 2022). "Diabetes Mellitus (DM) is characterized by chronic hyperglycemia resulting from deficiencies in insulin secretion, insulin action, or both." (PMID 36046788, 2022). "Type 2 diabetes mellitus was mainly caused by insulin resistance or insufficient insulin secretion, ginsenosides could promote insulin secretion, increased insulin sensitivity, and reduced blood glucose concentration, but will not increase the risk of hypoglycemia." (PMID 35548575, 2022). "Diabetes mellitus (DM) is a metabolic disorder syndrome caused by genetic and environmental factors, characterized by decreased insulin sensitivity, insulin deficiency, and impaired biological function." (PMID 35570291, 2022). "Due to the relationship between increased insulin levels and androgens, the treatment of hyperinsulinemia with pharmacological and nonpharmacological approaches is essential, notwithstanding the preclinical effects of high insulin levels and predisposition to diabetes." (PMID 36159086, 2022). "All the putative TFs have been reported to be implicated in diabetes and its related diseases, controlling skeletal muscle metabolism, ameliorating diabetic nephropathy pathology, modulating human pancreas development, and leading to the improvement of metabolic health and insulin sensitivity." (PMID 36368953, 2022). "Diabetes mellitus (DM), a complex disease featuring a deficiency or resistance to insulin, exposes individuals to hyperglycemia." (PMID 36248006, 2022). "Notably, SIRT4 lysine deacetylase activity is involved in the regulation of leucine metabolism, whose dysregulation causes elevated secretion of basal and stimulated insulin which in turn may lead to glucose intolerance and diabetes." (PMID 35409409, 2022). "The cluster “diabetes” is the largest one with 66,775 occurrences of “diabetes” as either cause or effect (eg, diabetes, #diabetes, diabetes mellitus) followed by “death” with 16,989 (eg, passed away, killed, died, suicide) and “insulin” (eg, insulin, insulin hormone) with 14,148 occurrences." (PMID 35852829, 2022). "It has been reported that insulin has a trophic effect on pancreatic acinar tissue, and insulin deficiency might cause pancreas atrophy through the insulin-acinar portal system, which is often impaired in diabetes." (PMID 36213198, 2022). "Diabetes mellitus (DM) is a group of metabolic diseases characterized by hyperglycemia, caused by deficiencies in insulin secretion and/or insulin action." (PMID 36465656, 2022). "Furthermore, increased risk of renal cell carcinoma has been observed in individuals with diabetes or obesity and light to moderate alcohol consumption improved insulin sensitivity and lowered the risk of T2D thus lowering the incidence of renal cell carcinoma." (PMID 35602135, 2022). "Diabetes Mellitus (DM) is characterized as a heterogeneous group of disorders causingdysfunction in the production/secretion/absorption of insulin, which results inhyperglycemia." (PMID 35112702, 2022). "In addition, human milk insulin was negatively associated with Streptococcaceae, indicating that it might be related to the occurrence and development of diabetes." (PMID 35185792, 2022). "Therefore, a combined evaluation of both triglycerides and insulin levels may serve as a more sensitive biomarker for early metabolic syndrome in adults free of diabetes, with a higher risk for cancer mortality compared to other ISIs and each surrogate alone." (PMID 35921366, 2022). "Furthermore, Abnormal lipid metabolism is associated with the pathogenesis of diabetes, which may be associated with impaired insulin reactivity and abnormal blood glucose control." (PMID 36684872, 2022).
diabetes (continued). "Diabetes mellitus (DM) is a group of metabolic diseases characterized by hyperglycemia, which is caused by defective insulin secretion, impaired insulin biology, or both." (PMID 36686651, 2022). "We thus mapped the mouse insulin secretion QTL to the human genome based on sequence alignment and asked whether the LECIF score could provide information in locating regions within the mapped mouse insulin secretion QTL that correspond to human diabetes GWAS variants." (PMID 33941776, 2021). "Given the different etiologies of the two forms of diabetes with respect to insulin availability, the similar association with PDAC and other malignancies also supports the concept that hyperglycemia, rather than hyperinsulinemia, may be the driving force between diabetes and cancer." (PMID 33467038, 2021). "Diabetes mellitus (DM) has been described as a metabolic disorder characterized by chronic hyperglycemia caused by impaired insulin secretion or impaired insulin action or both." (PMID 34068304, 2021). "However, calcineurin B1 deficiency may contribute to the development of diabetes mellitus as a result of insufficient insulin synthesis as age progresses." (PMID 34639164, 2021). "In line with previous studies in other countries, diabetics and obese people generally perceived less functional capacity and energy than healthy people, which is closely associated with characteristic problems in these patients such as resistance to insulin or oxidative stress." (PMID 33800585, 2021). "Although pancreatitis can lead to type 3c diabetes, due to collateral pancreatic β-cell injury and the loss of insulin secretion, emerging evidence from clinical and animal studies suggest that diabetes increases the severity of AP and thus endogenous insulin may be protective." (PMID 34282152, 2021). "Thus, mitochondrial dysfunction with subsequent elevated ROS levels might represent a common pathophysiological defect in diabetes mellitus as well as in AD-associated abnormal brain insulin and glucose metabolism." (PMID 34439505, 2021). "Nonetheless, several animal and human studies have reported that palmitoleic acid (16:1n-7) may enhance whole-body insulin sensitivity, increase hepatic FA oxidation, and improve blood lipid profile, and are associated with a low prevalence of diabetes and cardiovascular risk." (PMID 33898358, 2021). "Diabetes is caused by a relative deficiency of insulin compared to need, which can be caused by loss of β-cell and insulin secretion capacity, or decreased effectiveness of insulin due to development of insulin resistance in target tissues, or a combination of the two." (PMID 34159399, 2021). "A recent rat study of early onset insulin-deficient diabetes supported this hypothesis, by showing that subcutaneous insulin treatment cannot completely prevent several of the hippocampal-dependent behavioural and structural alterations linked with an increase in local 11β-HSD1 activity." (PMID 34970219, 2021). "Several of them in previous studies were found to be associated with insulin signalling, inflammation and adipogenesis, thereby suggesting their role, not only in sick fat or adiposopathy, but possibly also in the aetiology of cardiovascular and microvascular complications of diabetes." (PMID 34017037, 2021). "Diabetes mellitus (DM) is one of the most prevalent endocrine diseases worldwide, characterised by an increase in blood glucose levels caused by defective insulin secretion, action or both." (PMID 34361044, 2021). "Diabetes mellitus (DM), one of the most common metabolic diseases, is characterized by high blood glucose levels due to a deficiency of insulin in the body or insufficient insulin sensitivity." (PMID 33466863, 2021).